NOTCH2 (notch receptor 2)
Diseases named in the same sentence as NOTCH2 in open-access papers (continued):
Sharing a sentence is not in itself a finding about the gene and the disease.
breast tumors (6 papers, 2010 to 2023). "A recent study found some evidence of increased NOTCH2 expression in breast tumors in carriers of the G allele of rs11249433." (PMID 23977306, 2013). "It was reported that NOTCH1 and JAG1 are highly expressed in poorly differentiated breast tumors and are associated with poor survival, whereas NOTCH2 expression has been correlated to high rates of disease-free survival, suggesting antagonistic functions of Notch1 and Notch2." (PMID 32796631, 2020). "Thus, increased or persistent activation of NOTCH2 expression may favor development of ER+ breast tumors." (PMID 23977306, 2013). "In contrast, overexpression of Notch-2 in MDA-MB-231 cells significantly decreased tumor growth and increased apoptosis in vivo, suggesting that Notch-2 is a breast tumor suppressor." (PMID 21679465, 2011). "Interestingly, Notch-2 levels showed a moderate but significant increase upon PEA3 knockdown, which, upon further investigation, may prove to be advantageous, since it has been correlated with proapoptotic and breast tumor suppressive function." (PMID 21679465, 2011).
cervical carcinoma (6 papers, 2014 to 2024). A carcinoma arising from either the exocervical squamous epithelium or the endocervical glandular epithelium. "In cervical cancer, upregulation of Notch1 and Notch2 was associated with in-situ or invasive squamous cell carcinoma and adenocarcinoma, and it is thought that abnormal Notch signaling can promote the development of cervical cancer." (PMID 25381598, 2014). "GABPB1-AS1 can release the inhibition of its target gene Notch2 and promote the progress of cervical cancer by binding with miR-519e-5p." (PMID 36092924, 2022).
congenital heart disease (6 papers, 2017 to 2025). A heart disease that is present at birth. "We describe a case of ALGS with novel mutations of JAG1 and NOTCH2 genes in a newborn girl with complex congenital heart disease, bilateral dysplastic kidneys, and malrotation with volvulus." (PMID 28465853, 2017). "A heterozygous frameshift mutation in exon 34 of Notch2 (c.6426dupT) has been found in patients with HCS, resulting in severe congenital heart disease in these patients." (PMID 40104444, 2025). "Variations in NOTCH2, NOTCH3, TTN, TBX4, TBX10, TBX18, and TBXAS1 are associated with congenital heart disease." (PMID 29381953, 2017).
liver disease (6 papers, 2020 to 2024). "When considering living related transplantation, it is important to emphasize that donors with JAG1 and/or NOTCH2 mutations should be avoided as they may have unrecognized liver disease." (PMID 33172025, 2020). "NOTCH2 has been indicated in the development of hepatic diseases." (PMID 35322757, 2022). "Our findings underscore a novel molecular insights into MSCs-mediated immunomodulation by activating Notch2/COX2/AMPK/SIRT1 pathway and thus provide a new strategy for the treatment of liver inflammatory diseases." (PMID 35842731, 2022).
myeloma (6 papers, 2010 to 2024). "In particular, here we have directed our first effort to inhibit Notch2 activation trigged by the ligand Jagged2 on the basis of our interest in multiple myeloma, an hematological malignancy associated to Notch2/Jagged2 dysregulation." (PMID 29099834, 2017). "On the other side, Notch2 signalling triggered in osteoclast precursors by myeloma cell-derived Jagged ligands is key in activating tumor-associated osteoclast differentiation and bone destruction." (PMID 29099834, 2017). "Similarly, in multiple myelomas, Notch1, Notch2, and JAG1 were highly expressed in primary tumor samples, and JAG1-induced Notch activation drove myeloma cell proliferation." (PMID 25309874, 2014).
nasopharyngeal carcinoma (6 papers, 2019 to 2025). A carcinoma arising from the nasopharyngeal epithelium. "The downregulation of Notch2 in NPC (nasopharyngeal carcinoma) cells elicited a phenotypic shift from epithelial to mesenchymal, characterized by suppression of an epithelial marker and upregulation of a mesenchymal marker." (PMID 38791461, 2024). "Our previous study found that in nasopharyngeal carcinoma (NPC) cells, overexpression of Notch2 can inhibit epithelial-mesenchymal transition (EMT), which plays a vital role in mediating radiosensitivity." (PMID 34224316, 2021).
non-small cell lung carcinoma (6 papers, 2009 to 2022). A group of at least three distinct histological types of lung cancer, including non-small cell squamous cell carcinoma, adenocarcinoma, and large cell carcinoma. "For example, in a non-small cell lung cancer model, Notch2 mediates differentiation and has tumor suppressor function, whereas Notch1 promotes tumor initiation and progression." (PMID 29963552, 2018). "In fetal lung development, Notch signalling appears to be essential for the lung to achieve its normal size and Notch 1 and Notch 2 protein are frequently expressed in human non-small cell lung cancer with Notch3 mRNA expression being detected in 7 of 25 NSCLC cell lines." (PMID 19812696, 2009). "A study has shown that Notch2 was upregulated in non-small cell lung carcinoma (NSCLC) and promoted the proliferation of NSCLC cells." (PMID 23599800, 2013).
oligodendroglioma (6 papers, 2009 to 2014). A well-differentiated (WHO grade II), diffusely infiltrating neuroglial tumor, typically located in the cerebral hemispheres. "The oncogenic potential of Notch2 is indicated by the fact that the loss of Notch2 positively correlated with a favorable prognosis in small groups of patients diagnosed with oligodendroglioma and GBM." (PMID 25601901, 2014). "To confirm that the deletion extended to the centromere, we further performed LOH-associated SNP loci analysis on five selected 1p/19q oligodendroglioma cases using a panel of 39 single copy SNP (single-nucleotide polymorphisms) markers encompassing the NOTCH2 locus." (PMID 19119320, 2009). "Although Hs683 cells were established from a GBM, they display typical oligodendroglioma features, including 1p/19 co-deletion, temozolomide sensitivity, abundant integrin β4 and low integrin β1 expression, and only one Notch2 gene copy per diploid cell." (PMID 24278309, 2013). "Reminiscent of the better outcome of oligodendroglioma patients harboring 1p/19q loss, the minimal area of loss in GBM and the detection of homozygous deletions in oligodendroglioma converge to the Notch2 gene." (PMID 21078177, 2010). "For example, Notch2 status has been identified as a highly significant prognostic marker in GBM and oligodendroglioma independent of other mutation patterns." (PMID 23451269, 2013). "In oligodendrogliomas, Notch2 is frequently deleted and the corresponding protein is not detectable." (PMID 21078177, 2010).
Osteopenia (6 papers, 2017 to 2025). Osteopenia is a term to define bone density that is not normal but also not as low as osteoporosis. "Previously, we have shown the in vitro and in vivo ability of Notch2 ASOs to downregulate Notch2 expression and as a result improve the osteopenia of mice harboring a Notch2 gain-of-function mutation found in HCS." (PMID 39752389, 2025). "The ASO strategy was recently tested in an experimental mouse model of HCS termed Notch2tm1.1Ecan and characterized by a NOTCH2 gain-of-function and severe osteopenia secondary to increased osteoclastogenesis." (PMID 33519922, 2020). "Importantly, the administration of Notch2 ASOs in vivo ameliorated the osteopenia of HCS Notch2tm1.1Ecan heterozygous mice." (PMID 33519922, 2020). "The Notch2 gain-of-function model revealed sustained osteoclast activity, elevated number of osteoclasts and increased bone resorption, resulting in marked osteopenia, while osteoblast differentiation and function were not affected." (PMID 33572704, 2021).
small cell lung carcinoma (6 papers, 2013 to 2023). Small cell lung cancer (SCLC) is a highly aggressive malignant neoplasm, accounting for 10-15% of lung cancer cases, characterized byrapid growth, and early metastasis. "High Notch2 signalling has been shown to cause cell cycle arrest in small cell lung cancer (SCLC) cell lines by upregulating CKIs p21 and p27, and inhibitory phosphorylation of ERK1 and ERK2." (PMID 37608096, 2023). "Studies have demonstrated that Notch2 can be detected in bronchiolar epithelial cells, and plays important roles in small-cell lung cancer." (PMID 33549106, 2021). "Additionally, NOTCH2 is a marker of NE stem cells, which initiate NE reprogramming after injury and are the proposed origin of small cell lung cancer." (PMID 34657147, 2022). "Notch 1 is rarely expressed in small cell lung cancer (SCLC), whereas a subset of SCLC exhibit Notch 2 expression." (PMID 26497899, 2015). "In addition, KDM5A can also promote the occurrence of small-cell lung cancer by inhibiting the target genes NOTCH1 and NOTCH2." (PMID 35493099, 2022).
triple-negative breast carcinoma (6 papers, 2014 to 2021). An invasive breast carcinoma which is negative for expression of estrogen receptor (ER), progesterone receptor (PR), and human epidermal growth factor receptor 2 (HER2). "NOTCH3 and NOTCH2 mutations were detected in a subset of Chinese patients with triple-negative breast cancer." (PMID 33968723, 2021). "For instance, constitutively activating mutations in Notch1 and Notch2 are equally oncogenic in a subset of triple negative breast cancer (TNBC), despite the fact that Notch2 has been described as a tumor suppressor in TNBC cell lines." (PMID 27148486, 2016). "Both MSI-1 and MSI-2 were well-expressed in triple-negative breast cancer samples and showed strong correlations with Notch pathway elements Notch-1 and Notch-2." (PMID 32245259, 2020). "Moreover, ectopic expression of active Notch2 inhibited cell growth and induced apoptosis in triple-negative breast cancer cells, suggesting a tumor suppressor role for Notch2." (PMID 25229616, 2014).
cholangiocarcinoma (5 papers, 2018 to 2025). A carcinoma that arises from the intrahepatic biliary tree (intrahepatic cholangiocarcinoma) or from the junction, or adjacent to the junction, of the right and left hepatic ducts (hilar cholangiocarcinoma). "Given the reiterative use of NOTCH2 in mammalian bile duct biology, it is somewhat surprising that these early studies have identified NOTCH1 as essential for the formation of hepatocyte-derived cholangiocarcinoma." (PMID 37605966, 2023). "A previous study using a mouse model of HCC and cholangiocellular carcinoma (CCC) induced by the overexpression of v-Akt and N-Ras oncogenes in hepatocytes reported the different effects of the blockade of Notch1, Notch2, and Notch3 signaling on the tumor progression." (PMID 35064244, 2022).
depression (5 papers, 2016 to 2025). "Cluster 5 included NOTCH1 and NOTCH2, which may be associated with depression and anxiety-like behaviors." (PMID 41157308, 2025). "Finally, NOTCH2 which we identify here as downregulated at the level of translation, is a proposed biomarker for depression associated with PD64." (PMID 36746972, 2023). "Plasma NOTCH2 level may be a good blood biomarker for detecting patients of PD with depression." (PMID 30233306, 2018). "These clusters particularly involved genes related to regulatory subunits of cAMP-dependent protein kinases, such as PRKAR2A, cAMP-responsive element-binding pathway, circadian rhythms, such as CLOCK, ARNT1, CRY2, PER1, and PER2, and anxiety and depression, such as NOTCH1, NOTCH2 and ANK2." (PMID 41157308, 2025).
diabetic nephropathy (5 papers, 2018 to 2022). "However, there are already some findings that suggest the short-term effect of increased NOTCH2 activation is associated with a strong survival benefit for injured podocytes, which is lost in long-term models, such as diabetic nephropathy." (PMID 33924028, 2021). "It is well-known that NOTCH2 expression is downregulated once nephron maturation is achieved, except in the conditions of renal injuries, such as diabetic nephropathy and FSGS." (PMID 33924028, 2021). "Moreover, one recent study has defined Notch2 and Jagged1 as possible biomarkers for distinguishing moderate and severe stages of diabetic nephropathy." (PMID 36294921, 2022). "Our findings therefore suggest that Notch2-mediated renal tubular EMT could be a therapeutic target in diabetic nephropathy, and both LE and de-glycyrrhizinated LE could have therapeutic potential to attenuate renal tubular EMT and fibrosis." (PMID 31948095, 2020). "Additionally, these results could imply the role of the Notch2 transmembrane receptor in the tubular EMT process of distal tubular epithelial cells in diabetic kidney disease." (PMID 36294921, 2022). "In contrast, mice with podocyte-specific deletion of Notch2 were not protected against diabetic kidney disease development." (PMID 33519447, 2020). "Indeed, conditional deletion of Notch1, but not Notch2, in podocytes of mice with diabetic nephropathy abrogates glomerulosclerosis." (PMID 29398135, 2018).
lung adenocarcinoma (5 papers, 2016 to 2024). A carcinoma that arises from the lung and is characterized by the presence of malignant glandular epithelial cells. "Increased expression of Notch2 was found by RT-PCR in patients with lung adenocarcinoma compared to that in other histology types." (PMID 30470250, 2018). "Notch2 mRNA expression was comparable in peripheral CD4+ T cells between NC and lung adenocarcinoma patients (P=0.148) and in BALF CD4+ T cells between nontumor and tumor sites (P=0.288)." (PMID 30473538, 2018). "In the present study, we found that Notch1 mRNA, but not Notch2 mRNA, was elevated in both peripheral and lung-resident CD4+ T cells in lung adenocarcinoma patients." (PMID 30473538, 2018).
sarcoma (5 papers, 2019 to 2025). A usually aggressive malignant neoplasm of the soft tissue or bone. "Antitumor activity by single agents targeting the Notch signaling pathway, such as a γ-secretase inhibitor and a monoclonal antibody targeting Notch 2/3 receptors, have been observed in early phase clinical trials of sarcoma or desmoid tumors." (PMID 32939607, 2021). "Transcription factor genes on chromosome 1 such as NOTCH2 (deletion), PRKAB2 (amplification) and SELL (amplification) also shared similar copy number alterations in all three types of sarcomas." (PMID 30704460, 2019).
Sepsis (5 papers, 2018 to 2023). Sepsis is defined as life-threatening organ dysfunction caused by a dysregulated host response to infection. "In lipopolysaccharide (LPS)-induced sepsis, the levels of Notch signaling molecules, including Notch1, Notch2, Hes1, and intracellular domain of Notch (NICD), were increased." (PMID 29867921, 2018). "Pulmonary midkine inhibition ameliorates sepsis induced lung injury, which might via ACE/Ang II pathway and the participation of Notch 2 in the stimulation of ACE." (PMID 33639987, 2021). "Midkine inhibition ameliorates sepsis induced lung injury, which might via ACE/Ang II pathway and the participation of Notch 2 in the stimulation of ACE." (PMID 33639987, 2021).
Cirrhosis (4 papers, 2015 to 2022). A chronic disorder of the liver in which liver tissue becomes scarred and is partially replaced by regenerative nodules and fibrotic tissue resulting in loss of liver function. "In addition, we found that the expression level of miR-148a-5p in liver tissue of patients with cirrhosis was significantly decreased with the increase of Notch2 and Hes1 compared with the normal liver." (PMID 35883205, 2022). "Yet, we observed that Jag1, Notch 1, Notch 2, Notch 3, and Hey2 were significantly upregulated in both Ep+CIR and Ep+HCC cells as compared to Ep+NSCs, indicating the appearance of CSC like phenotype during advanced cirrhosis." (PMID 28176469, 2017). "By contrast, the NOTCH2 pathway was not activated in inflammation liver, cirrhosis liver and normal liver." (PMID 25985737, 2015).
endometrial cancer (4 papers, 2016 to 2025). Primary or metastatic malignant neoplasm involving the endometrium (mucous membrane that lines the endometrial cavity). "In the present series of patients with endometrial cancer of all types and stages we found that Notch2 and Jag1 protein expression has opposite prognostic impact." (PMID 30521558, 2018). "Also, as compared to low endometrial cancer grades, tumours with grade 3 were more frequently characterized with NOTCH2 and NOTCH3 protein overexpression." (PMID 35136410, 2022). "Beyond classic unfavorable prognostic factors in endometrial cancer, such as tumor type II, higher grade and more advanced stage, higher Ki67 labeling, expression of the PTEN, p16, Notch2 and Notch3 proteins, as well as MMR proficiency were associated with increased relapse and mortality risk." (PMID 30521558, 2018).
fibrosis (4 papers, 2017 to 2025). the formation of excess fibrous connective tissue in an organ or tissue in a reparative or reactive process. "It was reported that miR-18a-5p targeted NOTCH2 in high glucose-induced HAVECs, thus impeding cardiac fibrosis and epithelial-to-mesenchymal." (PMID 34649592, 2021). "We confirmed the higher protein expression of JAG1 and NOTCH2 in kidneys with fibrosis." (PMID 30226866, 2018). "Notch-2, rather than Notch-1, plays an important role in generating tubulointerstitial fibrosis in our myofibroblast and UUO models." (PMID 29101337, 2017).
metastatic cancer (4 papers, 2020 to 2025). A carcinoma which has spread from the original site of growth to another anatomic site. "Analysis of a few patients with metastatic cancer survive exceptionally longer than others under the same treatment identified multiple common mutations of NOTCH2, NF1, FANCD2, PIK3CB and EPHA5 in tumors that responded exceptionally well to treatments." (PMID 32600248, 2020). "NOTCH2, NOTCH2NL, KIF5B, and ERBB4 are highly expressed in primary cancer, while ERBB2, CLDN11 and CDK12 are overexpressed in metastatic cancer." (PMID 33441952, 2021). "Population-wide comparison between TT and LN single cells revealed that NOTCH2, NOTCH2NL, KIF5B, and ERBB4 are highly expressed in primary cancer, while CDK12, ERBB2, and CLDN11 are overexpressed in metastatic cancer." (PMID 33441952, 2021).
osteoarthritis (4 papers, 2023 to 2025). A noninflammatory degenerative joint disease occurring chiefly in older persons, characterized by degeneration of the articular cartilage, hypertrophy of bone at the margins and changes in the synovial membrane. "In accordance with the proposed role of NOTCH2 in inflammation, Notch2tm1.1Ecan mice are sensitized to the osteoarthritis that follows DMM surgeries and to the osteolytic actions of tumor necrosis factor α (TNFα)." (PMID 40345585, 2025). "Although one case of osteoarthritis in HCS has been reported, its association with the NOTCH2 gain-of-function was not established, and the prevalence of osteoarthritis cannot be estimated due to the rarity of the syndrome." (PMID 40345585, 2025). "Although the current work offered an initial understanding of the role of NOTCH2 in cartilage tissue homeostasis, it did not explore the role of NOTCH2 in osteoarthritis." (PMID 40345585, 2025). "From the XP-EHH analysis, NOTCH2 has been observed to mediate chondrogenesis differentiation in cartilage progenitor/stem cells and to play a role in chondrocyte maturation, and MGAT4C has presented with upregulated mRNA expression in osteoarthritis." (PMID 36833311, 2023). "Notch2tm1.1Ecan mice harbor a NOTCH2 gain-of-function and are sensitized to osteoarthritis, but the mechanisms have not been explored." (PMID 37865314, 2023).